CUL4B (cullin 4B)
Diseases named in the same sentence as CUL4B in open-access papers (continued):
Sharing a sentence is not in itself a finding about the gene and the disease.
tumor (45 papers, 2015 to 2026). "Overexpression of CUL4B is associated with poor prognosis, while downregulation reduces tumor cell proliferation and increases cell death." (PMID 40230836, 2025). "CUL4B expression was also significantly associated with tumor diameter (P = 0.006), lymph node metastasis (P = 0.028), extrathyroid invasion (P = 0.006), and the AJCC/TNM stage (P = 0.008)." (PMID 40203790, 2025). "We then investigated the role of CUL4B in tumor invasion via in vitro CUL4B loss‐of‐function experiments using transwell invasion assays." (PMID 34026424, 2021). "CUL4B has attracted considerable interest within the realm of oncology, primarily due to its pervasive overexpression across numerous human malignancies, which has been persistently linked to tumor advancement and aggressiveness." (PMID 40230836, 2025). "In addition, we revealed the findings demonstrating CUL4B’s association with oncogenesis and its important function as bio-marker for tumor diagnosis." (PMID 28630798, 2017). "Compared to the control group, the tumor in the CUL4B low-expression group of mice was significantly reduced." (PMID 40203790, 2025). "By preventing the accumulation and suppressive activities of MDSCs, the key E3 ubiquitin ligase component CUL4B disrupts the formation of a tumor-permissive niche, thereby eliciting profound antitumor effects." (PMID 40230836, 2025). "CUL4B also plays a role in potentiating anti-tumor immunity by restricting the activity of myeloid-derived suppressor cells (MDSCs)." (PMID 40230836, 2025). "CUL4B was crucial in driving tumor advancement and inhibiting differentiation in TC by facilitating the ubiquitin-mediated degradation of ARID1A, underscoring its potential as a therapeutic target." (PMID 40203790, 2025). "For instance, exosomal circKDM4A acts as a molecular sponge for miR-338-3p, alleviating its suppression of CUL4B to activate the ubiquitin-proteasome system, thereby fostering tumor proliferation and therapy resistance." (PMID 41357241, 2025). "Mechanistically, CUL4B wields its inhibitory influence on tumor progression through the manipulation of the immune microenvironment, thereby exerting tumor-restraining effects." (PMID 40230836, 2025). "This further underscores the tumor-suppressing function of CUL4B in the context of MDSC-mediated tumor progression." (PMID 40230836, 2025). "CUL4B exhibits a dual role in cancer biology, being highly expressed in numerous solid tumors and essential for maintaining tumor malignancy, thereby promoting oncogenesis." (PMID 40230836, 2025). "Our findings revealed that CUL4B expression was positively correlated with tumor progression and poor prognosis in TC." (PMID 40203790, 2025). "In myeloid-specific CUL4B KO knockout models, augmented tumor growth and metastasis correlate with elevated IL-6 secretion by MDSCs." (PMID 40230836, 2025). "More importantly, the abrogation of CUL4B function significantly hindered tumor progression in a DLBCL xenograft mouse model, underscoring its potential as a crucial therapeutic target." (PMID 40230836, 2025). "Cullin 4B (CUL4B), a member of the ubiquitin E3 ligase family, acts as tumor oncogene via inhibiting the tumor suppressor." (PMID 36969009, 2023). "Due to the well-known functions of TGF-β1 in the regulation of the tumor microenvironment, it is likely that CUL4B regulates the tumor microenvironment through TGF-β1 regulation." (PMID 37686215, 2023). "Confirming our previous data, the analyses showed that CUL4B expression was elevated in PM tumor tissue compared to normal pleura, and high CUL4B expression was associated with short the progression-free survival of PM patient cohorts." (PMID 37686215, 2023). "The novelty of our data is the unique effect of CUL4B in the regulation of TGFβ signaling in PM, which likely plays an important role in the regulation of the tumor microenvironment." (PMID 37686215, 2023).
tumor (continued). "Next, we analysed the survival and prognosis of tumour patients against CUL4B expression, and we found that the expression of CUL4B was closely related to recurrence and death of the patient, indicating a huge impact." (PMID 36385733, 2022). "CUL4B is a scaffold protein that is overexpressed in various solid malignancies and silences tumor suppressors by posttranscriptional means." (PMID 35909905, 2022). "After proving the importance of CUL4B in oxaliplatin resistance in vitro, we then performed subcutaneous tumour formation experiments in nude mice." (PMID 36385733, 2022). "NCBP1 was significantly overexpressed in LUAD, combined with CUL4B, which promoted the proliferation, migration and invasion of tumor cells." (PMID 36091687, 2022). "In vivo tumour formation assay also found that after CUL4B knockdown, the tumour was composed of significantly more epithelial cells than mesenchymal cells, showing that CUL4B can affect EMT and thereby affect drug resistance." (PMID 36385733, 2022). "We and others have recently demonstrated that CUL4B regulates the expression of several tumor suppressors, including MYCN, PIK3CA, HER2, SOX4, C-MYC and CDH2 at the posttranscriptional level." (PMID 35784474, 2022). "CUL4B was significantly upregulated in tumors, and CUL4B expression levels were positively correlated with tumor histological grades." (PMID 34026424, 2021). "While CUL4B acts as an oncogene in many solid tumors, in hematopoietic cells CUL4B exerts a tumor-suppressive effect by restricting the accumulation and function of myeloid-derived suppressor cells." (PMID 33869025, 2021). "The results showed that mice in the shSCR group developed tumors with as few as 100 cells, whereas those in the shCUL4B group did not develop any tumors, suggesting that the possibility of tumor formation was greatly reduced after CUL4B depletion." (PMID 34026424, 2021). "We then established five lines of CRC organoids and evaluated the effect of CUL4B expression on tumor organoid-forming capacity." (PMID 32054830, 2020). "The fact that CUL4B enhances the tumor-derived organoid-forming capacity suggested that CUL4B is involved in the enrichment of CSCs or cells with stem cell-related characteristics." (PMID 32054830, 2020). "Transgenic mice overexpressing CUL4B in the liver exhibited increased hepatocyte proliferation and accelerated tumor development after chemical exposure." (PMID 33233664, 2020). "Taken together, these data suggest that CUL4B promotes metastatic capacity and increases ability of tumor cells to colonize in the liver and lung." (PMID 32054830, 2020). "The overexpression and knockdown cell lines of Cul4B were then established to examine its potential role in the regulating of tumor malignant behaviors." (PMID 32622365, 2020). "Next, we used the mouse xenograft model to examine the effect of CUL4B knockdown on tumor growth by injecting CUL4B knockdown and control CCSCs into the left and right flank of the same nude mouse, respectively." (PMID 32054830, 2020). "We assessed the gene expression of CUL4A and CUL4B in 94 tumor tissues collected from MPM patients at diagnosis, surgery or relapse by quantitative real-time PCR (qPCR)." (PMID 33233664, 2020). "CCK8 assay revealed that overexpression of Cul4B promotes tumor proliferation while knockdown of Cul4B inhibits tumor proliferation." (PMID 32622365, 2020). "The number of tumor nodules was significantly reduced after the ablation of CUL4B in HCT116 and HT29 lines." (PMID 32054830, 2020). "Recently, more and more studies show that Cul4B plays an important role in the development of tumor." (PMID 32622365, 2020). "Cul4B promotes the proliferation and migration of tumor cells by ubiquitination of H2AK119 and transcription inhibition complex PRC2." (PMID 32622365, 2020). "Wnt synthesis inhibitors blocked the tumor growth with concurrent overexpression of CUL4B and SOX4 in vivo." (PMID 30872583, 2019).
tumor (continued). "Recently, we and others have demonstrated that CUL4B repressed tumor suppressors that are highly important in solid malignancies, including P16, PTEN, Wnt antagonists and IGFBP3 at their promoters." (PMID 30872583, 2019). "Tumours in which NCBP1 was silenced showed significantly lower levels of CUL4B mRNA expression (P < .01)." (PMID 31448526, 2019). "Ectopic expression of CUL4B (CUL4B) significantly promoted the growth of DU145 tumor xenografts, compared to a control group (Vector)." (PMID 30872583, 2019). "CUL4B is overexpressed in many types of human tumor cells, and this overexpression has been shown to influence the malignant behavior of these cells in regard to vascular invasion, histological differentiation, and metastasis." (PMID 31260508, 2019). "Our in vivo study showed that silencing of NCBP1 reduced tumour size as well as affecting the morphological and biochemical characteristics of the tumours and simultaneously decreasing CUL4B expression." (PMID 31448526, 2019). "As expected, we found the activation of the TNF‐α/NF‐κB axis, and the knockdown of TNFR1, RelA, RelB, c‐Rel, and CUL4B showed similar effects on the proliferation, invasion, colony formation, and the in vivo tumor forming ability of cells." (PMID 29377600, 2018). "Recently, studies have shown that CUL4B was overexpressed in a multitude of solid neoplasms and affect the expression of several tumor suppressor genes." (PMID 28630798, 2017). "Down-regulation of CUL4B can inhibit cell proliferation, lead to cell cycle S phase arrest and DNA replication abnormalities, which will promote tumor cell apoptosis." (PMID 28630798, 2017). "Western blot showed that CUL4B protein was upregulated in 66.7% of tumor tissues when compared to adjacent normal tissues." (PMID 28164432, 2017). "Immunohistochemical staining in esophageal, lung, gastric, colon, pancreatic, cervical, renal, liver, and bladder tumor and matched tissues, showed a significant overexpression of CUL4B in tumor tissue." (PMID 28630798, 2017). "Given the important roles of miR‐194 cluster genes in repressing CUL4B and inhibiting tumor progression in NSCLC, miR‐194 mimics should be explored as a potential therapeutic agent." (PMID 28164432, 2017). "CUL4B has previously been reported to be up-expressed in many malignancies and appears to be positively correlated with tumor progression." (PMID 28630798, 2017). "For example, knockdown of the tumor genes such Cul4A, Cul4B, and Wdr23 increased double-stranded DNA breaks following changes in cell cycle." (PMID 26942699, 2016). "The liver/body weight ratio was higher in CUL4B transgenic mice because of the increased tumor masses." (PMID 25945838, 2015). "At 50 weeks after DEN treatment, all CUL4B transgenic mice and wild-type mice developed tumors, but the tumor masses in transgenic mice were significantly larger." (PMID 25945838, 2015). "Histological analysis of tumor regions showed that proliferating (PCNA-positive) cells were more abundant in CUL4B transgenic mice than in littermate control mice." (PMID 25945838, 2015). "Considering the environment of KRAS-promoted lung adenocarcinoma, CUL4B exerts its tumor-suppressing capabilities via intricate epigenetic processes that encompass coordinated interplay with HDACs, ultimately inhibiting the transcription of C-X-C motif chemokine ligand 2 (CXCL2)." (PMID 40230836, 2025). "Our findings show that CUL4B expression correlates with tumor progression and poor prognosis in TC." (PMID 40203790, 2025). "In summary, our data suggest that CUL4B overexpression is important for tumor cell growth and survival and may drive PM aggressiveness via the regulation of TGF-β1 expression and, furthermore, reveal a new mechanism of action of pevonedistat." (PMID 37686215, 2023).
tumor (continued). "Another study revealed that miR-381 and miR-489, which are downregulated through gastric tumorigenesis, directly target Cullin 4B (CUL4B), as a tumor-promoting gene, prevents GC cellular growth, migration and invasion through blocking the Wnt/β-catenin pathway." (PMID 37386429, 2023). "We showed that CUL4B is important for tumor cell growth, similar to its paralog, CUL4A." (PMID 37686215, 2023). "It shows that CUL4B in vivo can indeed affect the occurrence of oxaliplatin resistance in tumours." (PMID 36385733, 2022). "In order to study the relationship of CUL4B in the development of CRC, we analysed the difference in expression of CUL4B between tumour tissue and normal tissue adjacent to the tumour (NAT) in TCGA, and found that the expression of CUL4B in tumours was significantly higher than that of its NAT." (PMID 36385733, 2022). "Finally, by comparing the tumour size and weight, we found that the tumour volume in the CUL4B knockdown group was significantly higher than that of the control." (PMID 36385733, 2022). "Furthermore, consistent with our results in vitro, CUL4B significantly enhanced the tumor burden of NOD/SCID mice, possibly by stimulating an increase in the CSC population." (PMID 34026424, 2021). "However, deletion of CUL4A and CUL4B in mouse embryonic fibroblasts, as well as cultured tumor cells, results in growth retardation, suggesting that the CRL4 E3 ligase activity plays an essential role in growth." (PMID 34604860, 2021). "Therefore, CUL4B potentially promotes breast tumorigenesis by inducing a stem‐like state and enhancing their self‐renewal and tumor‐initiating capacities." (PMID 34026424, 2021). "As expected, knockdown of CUL4B reduced tumor volumes and tumor weight." (PMID 33869025, 2021). "Moreover, in 14 of 15 selected paired samples of each tumor grade, the mRNA expression of CUL4B was upregulated in tumor tissues compared to in adjacent tissues." (PMID 34026424, 2021). "Knockdown of CUL4B in PDOs led to smaller tumor organoids and decreased organoid-forming capacity from single cells, whereas overexpression of CUL4B increased this capacity, suggesting that CUL4B plays oncogenic roles in CRC." (PMID 32054830, 2020). "CUL4B promotes tumor expansion and metastasis capacity in xenograft." (PMID 32054830, 2020). "Moreover, patients with Cul4B positive tumor samples had higher recurrence rate and lower survival rate than those with negative tumor samples." (PMID 32622365, 2020). "CUL4B was significantly upregulated in 75 tumor tissues compared with paired adjacent tissues." (PMID 32054830, 2020). "Univariate and multivariate analysis revealed that tumor grade and intratumor Cul4B expression are independent risk factors of patient disease-free survival while tumor grade, FIGO stage and intratumor Cul4B expression are identified as independent risk factors of patient overall survival." (PMID 32622365, 2020). "CUL4B is frequently overexpressed in multiple kinds of solid tumor and functions to promote cell cycle progression and metastasis by epigenetically repressing tumor suppressors including miRNAs21–24." (PMID 32054830, 2020). "Cul4B has different functions in the oncogenesis and progression of tumor." (PMID 32622365, 2020). "Since NSC1892 specifically targeted the CUL4A/4B-DDB1 interactions, we speculated that it should also be effective to inhibit the cell growth of other CUL4A- or CUL4B-overexpression tumor cells, not only CRC cells." (PMID 32140073, 2020). "Western blot analysis revealed that Cul4B expression is upregulated in tumor tissues." (PMID 32622365, 2020). "Physiologically, the inhibition of the TNF‐α/NF‐κB/CUL4B axis significantly reduced proliferation, invasion, and colony formation, induced cell cycle arrest at the S phase, and attenuated the in vivo tumor forming ability, and the overexpression of CUL4B can greatly reverse these effects." (PMID 29377600, 2018).
tumor (continued). "High expression of CUL4B expression was reported to be related to tumor histological differentiation, invasion, distant metastasis, tumor size, lymph node metastasis, overall and recurrence rate, as well as disease-free survival in breast, colorectal, cervical, oesophageal and lung cancers." (PMID 28630798, 2017). "Importantly, miR‐194 levels were negatively correlated with CUL4B protein levels in these tumor tissues." (PMID 28164432, 2017). "Expression levels of CUL4B were significantly correlated with tumor size (P = 0.019)." (PMID 28164432, 2017). "Then, we tested the roles of CUL4B in tumor growth in vivo in a xenograft model." (PMID 28164432, 2017). "Compared to CUL4A, reports about the relationship between CUL4B and tumor are lack." (PMID 26460955, 2015). "Moreover, most of the liver tumors of CUL4B transgenic mice were larger than 2 mm, with the maximal tumor diameter of 4.5 mm, compared to 1.6 mm in littermate control mice." (PMID 25945838, 2015). "Furthermore, we found CUL4B could also significantly enhanced the sensitivity of mouse subcutaneous tumors to trametinib and dabrafenib treatment, resulting in tumor growth retardation." (PMID 40203790, 2025). "Notably, depletion of CUL4B or MTA1 in CXXC5-overexpressing tumors led to a diminished effect of CXXC5 overexpression; consistently, the decrease in tumor growth associated with CXXC5 knockdown could be rescued by the simultaneous silencing of TSC1." (PMID 36539038, 2023). "Furthermore, it is important to identify whether CUL4B upregulation regulates other cells and immune cells in the tumor microenvironment." (PMID 37686215, 2023). "Furthermore, by studying the effect of CUL4B on cell invasion of drug‐resistant cell lines, we found that knocking down CUL4B can significantly reduce the invasion ability of drug‐resistant tumour cells, indicating that CUL4B is an important cause of oxaliplatin resistance." (PMID 36385733, 2022). "Thus, SIRT1 and CUL4B are potential oncogenes and biomarkers and may serve as targets for tumor therapy." (PMID 34163012, 2021). "Some evidence said that CUL4B up-regulation in tumor cells might be regulated through miRNAs." (PMID 34338146, 2021). "CUL4B knockdown during signaling pathway activation directly leads to complete collapse of the network function and the signal cannot be transmitted, suggesting that CUL4B is a key and necessary factor in these pathways that play essential roles in promoting tumor metastasis." (PMID 34026424, 2021). "Transcriptomic profiling of TCGA datasets revealed significant up-regulation of CUL1, CUL2, CUL4A, CUL4B, CUL5, CUL7, and CUL9 in tumor tissues, with higher expression correlating with advanced stage and poorer survival, particularly for CUL5 and CUL7." (PMID 42021323, 2026). "To address the role of CUL4B as a prognostic marker in CRC, we examined CUL4B expression by immunohistochemistry in tissue microarrays comprising tumor tissues and adjacent tissues from 75 cases of CRCs." (PMID 32054830, 2020). "To evaluate the correlation between FOXO3A and CUL4B expression levels, we determined the expression of FOXO3A and CUL4B in SCC and SCLC tumor tissues by immunohistochemical staining." (PMID 32587774, 2020). "Previously we demonstrated that CUL4B can catalyze H2AK119 monoubiquitination and, in cooperation with PRC2, promote epigenetic silencing of tumor suppressors, leading to increased degree of malignancy." (PMID 25945838, 2015). "In summary, this study provided compelling evidence that CUL4B knockdown may be a promising strategy for treating HCC and increasing tumor cell sensitivity to oxaliplatin therapy." (PMID 41392287, 2025). "Collectively, these findings support the critical role of CUL4B and MLN4924 in tumor metabolism." (PMID 40419474, 2025). "Thus, the majority of CUL4B is localized in the nucleus, whereas CUL4A is mainly localized in the cytoplasm of cells, including mesothelioma tumor cells." (PMID 37686215, 2023).